BRAF (B-Raf proto-oncogene, serine/threonine kinase)
Diseases named in the same sentence as BRAF in open-access papers (continued):
Sharing a sentence is not in itself a finding about the gene and the disease.
colon carcinoma (continued). "Although there was statistically significant publication bias for the BRAF prevalence analyses, the addition of hypothetical “missing” studies did not significantly change the estimate of BRAF prevalence in right‐ or left‐sided colon cancers." (PMID 31856410, 2020). "On the contrary, the five remaining colon cancer cell lines, namely SW48, DIFI, MICOL24, CACO-2 and E705, showed no hyperactivating mutations in KRAS, NRAS, BRAF and PIK3CA genes, with the E705 cell line carrying a silent mutation in PIK3CA gene." (PMID 33233823, 2020). "Overall, our results suggest a molecular sub-cluster of colon cancer cells with low CDX2 and VDR expression is sensitive to chemotherapy, BRAF inhibitors and PI3K-mTOR inhibitors treatment and provide an example of translation of cancer classification to subgroup guided therapies." (PMID 31596728, 2019). "One colon cancer with a likely benign variant demonstrated MLH1 loss and BRAF mutation, but other nonpathogenic variants showed sustained MMR and microsatellite stability." (PMID 31386297, 2019). "In contrast, 95% of BRAFV600E mutant colon cancer patients do not respond to BRAF inhibition monotherapy." (PMID 31083627, 2019). "At variance with melanoma, colon cancers harboring BRAF (V600E) oncogenic lesions are not responsive to treatment with vemurafenib." (PMID 29652830, 2018). "Finally, a seven-gene panel showed high sensitivity and specificity in identifying BRAF-mutant, CIMP-high, and MLH1-silenced colon cancers." (PMID 29652830, 2018). "BRAF (V600E) mutant colon cancers may benefit from a combination therapy consisting of BRAF and EGFR inhibitors; EGFR and BRAF (V600E) inhibitors synergize to induce apoptosis of colorectal cells and to suppress colorectal tumor growth in a xenograft model." (PMID 28499452, 2017). "FTD showed a broad spectrum of anticancer activities against various colon cancer cell lines, irrespective of KRAS or BRAF mutation status, with IC50 values ranging from single to low double‐digit micromolar concentrations." (PMID 28486761, 2017). "Indeed we observed the same mechanism in three patient-derived colon cancer cell lines carrying BRAFV600E (Pt-1), KRASG13 (Pt-3) and wt BRAF and KRAS (Pt-2)." (PMID 29312543, 2017). "While cetuximab monotherapy was not effective against EGFR− RASwt, EGFR+ RASmut, and EGFR+ BRAFmut cells, A-PBNK were able to initiate lysis of EGFR+ colon cancer cells irrespective of RAS or BRAF status." (PMID 28220124, 2017). "To explore how different mutations change the response of tumor cells to drugs we treated CaCO2 (wildtype for BRAF and KRAS), HCT116 (KRASG13D), and HT29 (BRAFV600E) colon carcinoma cells with the MEK inhibitor AZD6244 or with the RAF inhibitor Sorafenib for various periods of time." (PMID 26799289, 2016). "In support, as a HSP90 client protein, Akt was only diminished by AUY922 in wild-type but not mutant BRAF colon cancer cells." (PMID 27391062, 2016). "KRAS, BRAF and NRAS mutations do not have major prognostic value in stage II and III colon cancer, subtypes of gene mutations should be further investigated for a better understanding in CRC." (PMID 27074743, 2016). "Nevertheless, it did not affect the expression of Akt in mutant BRAF colon cancer cells, suggesting that CDC37 is not essential for chaperoning Akt in the cells." (PMID 27391062, 2016). "Similar to AUY922, knockdown of the major isoforms of HSP90, HSP90α/β induced cell death in wild-type BRAF colon cancer cells, but did not significantly impinge on survival of mutant BRAF colon cancer cells." (PMID 27391062, 2016). "Nevertheless, CDC37 did not appear to play a role in wild-type BRAF colon cancer cells, in that AUY922 alone inhibited Akt expression in the cells." (PMID 27391062, 2016).
colon carcinoma (continued). "In the present study, the effect of KRAS/BRAF/PIK3CA oncogenic pathways on the autophagic cell properties and on main components of the autophagic machinery like p62 (SQSTM1), Beclin-1 (BECN1) and MAP1LC3 (LC3) in colon cancer cells was investigated." (PMID 26802026, 2016). "Of note, although Akt is a client protein of HSP90, AUY922 did not trigger any change in Akt expression in mutant BRAF colon cancer cells even at 16 hours when Akt activation was significantly suppressed." (PMID 27391062, 2016). "However, to our surprise, treatment with AUY922 only moderately reduced the expression of mutant BRAF while it abolished the expression of other HSP90 client proteins such as CRAF and SKP2 in mutant BRAF colon cancer cells." (PMID 27391062, 2016). "In addition, we demonstrate that reactivation of ERK is due to incomplete degradation of mutant BRAF by AUY922, whereas reactivation of Akt is triggered by the activity of CDC37 in mutant BRAF colon cancer cells." (PMID 27391062, 2016). "We recover a strong association between BRAF mutation and CIMP-positive colon tumors but no specific association with other tumor types." (PMID 26463173, 2015). "The role of BRAF V600E and KRAS mutations in the classification of early stage colon cancer is not well-defined." (PMID 25956750, 2015). "Colon cancer cells with and without oncogenic mutations such as KRAS and BRAF mutations were treated with erlotinib, an inhibitor of epidermal growth factor receptor, in order to detect the impact of these mutations on Raman spectra of the cells." (PMID 26168967, 2015). "Given that gene mutations (KRAS, BRAF and PIK3CA) influence cetuximab sensitivity, we chose two cell lines (Caco-2 and DiFi) that express wild-type KRAS, BRAF and PIK3CA, paralleling the molecular features of colon cancer patients who are most likely to respond to cetuximab." (PMID 24714091, 2014). "Interestingly, in spite of a tremendous amount of available literature on biomarkers in CRC, only a few biomarkers are nowadays used in daily clinical practice, such as KRAS, BRAF, MSI and the Oncotype DX® Colon Cancer Assay." (PMID 24759962, 2013). "Macroscopically, BrafV637E-induced neoplasia resembled human BRAF mutant colonic tumors, which frequently show a nonpolypoid sessile growth pattern." (PMID 23845441, 2013). "As previously observed the presence of mutant BRAF in colon cancer cells, does not predict cell sensitivity to PLX4720 nor did BRAFV600E overexpression in the mutational permissive background of Caco-2 cells." (PMID 21738740, 2011). "To identify molecular modifiers in currently resistant cells that influence the sensitivity of BRAF mutant cells to TRAIL induced apoptosis, we recorded a panel of colon cancer cell lines to determine their response to the BRAF inhibitor PLX4720, which targets the mutated V600E form of BRAF." (PMID 21738740, 2011). "Although our study did not identify a cause for MLH1 methylation in sporadic MSI-H colon cancer with an age of onset below 50 years, we observed methylation to be almost restricted to the MLH1 locus in patients without a BRAF mutation." (PMID 20444249, 2010).
colon carcinoma (continued). "Molecular analysis, including oncogenic alterations (KRAS/NRAS/BRAF), mismatch repair (MMR) status, and microsatellite instability status, is recommended for mCRC according to the National Comprehensive Cancer Network (NCCN) Guidelines Version 1.2022 for colon cancer." (PMID 37302081, 2023). "While mutant BRAF was shown to be among Hsp90 several clients, Hsp90 inhibition failed to abolish mutant BRAF in colon cancer, suggesting that it may not be solely, nor heavily dependent on Hsp90 for its stabilization." (PMID 36012578, 2022). "Our results demonstrated in univariate analysis that the clinico-pathological and molecular characteristics associated with DDR1 expression in colon adenocarcinoma were: male sex, left colon tumor localization, BRAF wild-type status, and absence of the expression of the serrated marker Annexin A10." (PMID 35205677, 2022). "However, BRAF inhibitor monotherapy showed a low response rate in BRAF-MT mCRC because rebound feedback with increased signaling through the epidermal growth factor receptor (EGFR) pathway after BRAF inhibition occurs in colon cancer." (PMID 35625987, 2022). "However, histology specific approaches, such as combination of BRAF, MEK, and EGFR inhibition in BRAF V600-mutant colon cancer demonstrate, may hold promise as well." (PMID 33216832, 2020). "Recently, Russo and colleagues provided evidence suggesting that colon cancer patients undergoing targeted therapy by inhibitors of EGFR (epidermal growth factor receptor) and/or BRAF (serine/threonine-protein kinase B-Raf) might also become resistant to these treatments by a similar mechanism." (PMID 32075223, 2020). "This study found that BRAF mutation status and KRAS mutation status were not distinctive in the association between low-dose aspirin use and a survival benefit in patients with colon cancer." (PMID 28125730, 2017). "Our in-vitro assays confirmed that BRAF and MEK were inhibited by MBZ in the nM range, with MBZ inhibiting both BRAFV600E and BRAFWT with a Kd of 210 and 230 nM, respectively, in agreement with previous results with a kinase screen of MBZ, chosen for its ability to inhibit colon cancer growth." (PMID 28157711, 2017). "In colon cancer, ERMP1 is expressed irrespective of KRAS and /or BRAF mutational status." (PMID 27566589, 2016). "While the association between lineage and mutation proved a stronger predictor than lineage or mutation alone, in many cases the associations remained weak and in some cases such as BRAF and sensitivity to the MEK inhibitor in colon cancer have not been validated in clinical studies." (PMID 23577104, 2013). "Additionally, evaluation of BRAF in stages II and III colon cancers showed that BRAF mutation was a negative prognostic factor for overall survival in patients." (PMID 22792460, 2012). "Furthermore, the current results indicate a role of mutations in KRAS, PIK3CA, and/or BRAF, and/or MMR deficiency in the etiological pathway between physical inactivity and colon cancer risk in women, but not men, and it seems that in particular PIK3CA mutations are involved in this association." (PMID 35546360, 2022). "Nowadays, molecular biomarkers that could affect the prognosis of stage IIA colon cancer such as microsatellite instability (MSI) and BRAF V600E mutation that have been intensively studies, were not included into our analyses, which might result into bias to some extent." (PMID 30815388, 2019).
colon carcinoma (continued). "In the proximal colon cancer network, KRAS mutation tended to be mutually exclusive only with BRAF mutation, indicating that the observed negative correlations of KRAS mutation with methylation-related markers and other biomarkers might be confounded by MSI-high in our earlier analysis." (PMID 28623901, 2017). "Another limitation of this study is the lack of molecular profiling (e.g., RAS, BRAF and MIS status), which have a critical role in colon cancer prognosis." (PMID 41010971, 2025). "We reviewed the previous literatures with keywords “colon cancer,” “KRAS,” “NRAS,” and “BRAF,” and there was no agreed conclusion of the driver gene’s role in CRC patients." (PMID 36862900, 2023). "Everolimus treatment disrupts the S6K1-IRS-2/PI3K negative feedback loop, leading to BRAF V600E-dependent activation of ERK and Mcl-1 stabilization in colon cancer cells, which in turn blocks the crosstalk from the death receptor to mitochondria." (PMID 27351224, 2016). "A lack of response to BRAF inhibitors could also be due to overexpression of resistance pathways, notably EGFR as is seen in colon cancer." (PMID 40869231, 2025). "Moreover, in mismatch repair-proficient BRAF-V600E-mutant colon cancers, combined EGFR and BRAF/MEK therapy is not cross-resistant with standard chemotherapy, suggesting new rational combination treatment strategies." (PMID 39626159, 2024). "After removing studies that did not specifically separate rectal tumors from left‐sided tumors, the prevalence among left‐sided colon tumors did not change substantially from the original analyses (RAS: 36.4% vs 32.4%, KRAS: 34.7% vs 35.8%, BRAF: 4.4% vs 4.3%)." (PMID 31856410, 2020). "And a sub-cluster of colon cancer patients with lack of VDR expression could benefit from adjuvant chemotherapy, BRAF inhibitors and PI3K-mTOR inhibitors treatment." (PMID 31596728, 2019). "And the sub-cluster of colon cancer patients with lack of VDR expression could benefit from adjuvant chemotherapy, BRAF inhibitors and PI3K-mTOR inhibitors treatment." (PMID 31596728, 2019). "In vitro cytotoxicity experiments using colon cancer primary tumors and cell lines COLO320, Caco-2, SW620, SW480 and HT-29, demonstrated that PBNK cells are cytotoxic for a range of tumor cells, regardless of EGFR, RAS or BRAF status and at low E:T ratios." (PMID 27314237, 2016). "Towards this end, when PLX4720 was co-administered with TRAIL, in TRAIL sensitive DLD-1 cells, TRAIL induced apoptosis was abrogated indicating wild-type BRAF and not mutant KRAS, also present in DLD-1, as the exclusionary factor for colon cancer treatment with PLX4720." (PMID 21738740, 2011).
papillary thyroid carcinoma (548 papers, 2004 to 2026). "Subsequent fine-needle aspiration cytology of the nodule at the left inferior pole demonstrated atypical cells suggestive of papillary thyroid carcinoma, and molecular testing confirmed the BRAF V600E mutation." (PMID 41559985, 2026). "Further investigation identified papillary thyroid carcinoma harboring a BRAF V600E mutation, after which neurological symptoms stabilized following thyroidectomy." (PMID 42233015, 2026). "This distribution aligns with the known mutational landscape of indeterminate thyroid nodules, in which RAS-type mutations predominate in follicular-patterned lesions, whereas BRAF V600E is typically associated with papillary carcinoma morphology." (PMID 41595518, 2026). "We present the first reported case of ICI-induced granulomatous sialadenitis in a male patient in his mid-fifties with BRAF-V600E-mutated papillary thyroid carcinoma who received sequential treatment with BRAF/MEK inhibitors followed by pembrolizumab." (PMID 41646709, 2026). "We present the case of a 37-year-old woman with BRAF V600E-mutated papillary thyroid carcinoma (PTC) who developed persistent dysphagia following total thyroidectomy as a result of a postoperative surgical complication." (PMID 41695167, 2026). "To illustrate the molecular testing potential of CytoMatrix, we performed targeted analysis for the BRAF V600E mutation, the most common genetic alteration in papillary thyroid carcinoma." (PMID 41303583, 2025). "BRAF V600E mutation in papillary thyroid cancer and its effect on postoperative radioiodine (131I) therapy: should we modify our therapeutic strategy?" (PMID 40977817, 2025). "In contrast, conventional papillary carcinomas (those forming papillae) are predominantly associated with BRAF p.V600E or BRAF V600E-like mutations, including RET and NTRK rearrangements." (PMID 41175860, 2025). "In papillary thyroid cancer, the incidence of BRAF mutations ranges from 45% to 50.9%, with dabrafenib and trametinib combination therapy yielding an OS of 14.5 months, PFS of 6.7 months, and ORR of 56%." (PMID 40896440, 2025). "After a right thyroid lobectomy, pathology revealed a hidden non-BRAF-mutated papillary thyroid carcinoma." (PMID 41641291, 2025). "The specificity of BRAF mutation in the diagnosis of papillary thyroid carcinoma (PTC) is nearly 100% but its sensitivity is below 35%." (PMID 39850836, 2025). "BRAF V600E mutation status detection facilitates prognosis prediction in papillary thyroid carcinoma (PTC)." (PMID 40395668, 2025). "About 50% of papillary thyroid cancers and 24.1% of follicular thyroid cancers harbor a BRAF V600E mutation." (PMID 40869231, 2025). "As the core driving gene mutation in papillary thyroid carcinoma, the continuous activation of the BRAF V600E signaling pathway is key to tumorigenesis, development, and the maintenance of the malignant phenotype." (PMID 41311976, 2025). "BRAF p.V600E mutation is the most common molecular driver identified in papillary thyroid carcinomas (PTCs, 58.5–86.8%)." (PMID 40111709, 2025). "On the other hand, mutations in RAS genes are less common compared to BRAF gene mutations and have been reported in the follicular variant of papillary thyroid cancers." (PMID 39744583, 2025). "BRAF V600E mutation is a key oncogenic driver commonly found in papillary thyroid carcinoma (PTC) and anaplastic thyroid carcinoma (ATC)." (PMID 40844731, 2025). "Evidence suggests both BRAF-positive PDTC and ATC harbor regions of preexisting papillary carcinoma, affirming BRAF mutations in well-differentiated and dedifferentiated components." (PMID 40271195, 2025). "The BRAF V600E gene mutation, strongly associated with papillary thyroid carcinoma, is widely used as a biomarker for TN diagnosis in clinical practice." (PMID 40093750, 2025).